CD63 (CD63 molecule)
Diseases named in the same sentence as CD63 in open-access papers (continued):
Sharing a sentence is not in itself a finding about the gene and the disease.
tumor (continued). "Targeting the hypoxia/CD63/exosomal lactate axis may represent a promising novel therapeutic strategy to restore anti-tumor immunity in UM." (PMID 41573746, 2025). "This incremental binding efficacy correlated with the strength of the effect of the glycosylation variants on tumor cell proliferation and survival, corroborating that the tumor-promoting cytokine-like effect of differentially glycosylated TIMP-1 was mediated by its interaction with CD63." (PMID 40345589, 2025). "The researchers knocked out MMP3 in tumor organoids, highlighting MMP3’s dual role in tumoroid structure and EV integrity, showing that MMP3-rich EVs rescue proliferation and CD9/CD63 expression in deficient organoids, thereby positioning MMP3 as a key modulator of tumor EV function." (PMID 40806235, 2025). "Importantly, tumor cell survival and proliferation-promoting activity via CD63 were dependent on TIMP-1 glycosylation, which required N30-glycosylation." (PMID 40345589, 2025). "Each distinct tumour type or genotype might regulate the amount of aEGFR, tEGFR, and CD63 EV-carrying forms of such EGFR analytes." (PMID 38830977, 2024). "However, whilst the anti‐CD63‐APC or anti‐CD9‐PE fluorescence were well‐detectable in the fractions F16‐F17 in tumour samples (red, violet lines), it remained at the detection limit in the samples of healthy donors." (PMID 39441012, 2024). "According to this network, we found that the exosome markers CD81, CD9, CD63, and TSG101 were associated with ANXA9, suggesting that ANXA9 may exist in exosomes in tumor tissues." (PMID 37294149, 2023). "As control, we used mice bearing mEER tumor cells carrying the PGK:CD63-eGFP expression cassette." (PMID 36735677, 2023). "In addition, a low dose of TM decreases exosome production in carcinoma cells, and Xbp1 depletion significantly decreases the numbers of exosomes and exosome markers, such as TSG101 and CD63, produced from tumor cells." (PMID 37524131, 2023). "Because our data suggest that the CD63/81+ sEV subpopulation in RB AH may be tumor-derived, we propose that the contents of these sEVs warrant further research." (PMID 37410475, 2023). "We observed a significantly dominant subpopulation of CD63/81+ sEVs in RB eyes, and we hypothesize that these sEVs are tumor-derived." (PMID 37410475, 2023). "In addition, this sensing platform can determine four different tumor cell types (4T1, Hela, HepG2, and A549) using surface proteins corresponding to aptamers 1 and 2 (CD63 and EpCAM) and showcases good specificity in serum samples." (PMID 37050576, 2023). "In addition, the results of western blot revealed the expression of exosome specific marker proteins CD63, CD9, TSG101 (tumor susceptibility gene) in the supernatant of MDA-MB-231 cells, which further confirmed the presence of exosomes in BC cell supernatant." (PMID 37056561, 2023). "Flow cytometric analysis revealed that, as expected, the immune cell subsets most frequently interacting with tumor cells (as measured by tEV uptake) were MHC-II+ Mac (21.3% of total CD45+ CD63-GFP+ cells), followed by B cells (20.6%) and Neu (13%), similarly to what we observed before." (PMID 36735677, 2023). "The CD63/81+ sEV subpopulation was also highest in AH from RB eyes with more significant tumor burden, further supporting this hypothesis." (PMID 37410475, 2023). "The CD63 tetraspanin is involved in cell adhesion, activation, differentiation and tumor invasion." (PMID 36466886, 2022). "Generally, immuno‐based microfluidic and microarray technologies have utilised tetraspanins (CD9, CD81 and CD63) and tumour‐cell surface associated markers such as EpCAM, CA125, CD19, EGFR, EGFRvIII, podoplanin and PDGFR for on‐chip capture of tumour‐EV sub‐populations." (PMID 36239734, 2022).
tumor (continued). "These novel findings further provided molecular insight into TIMP-1-mediated chemotherapy resistance involving glycolytic tumor metabolism and extracellular acidosis in addition to the previously characterized CD63/integrinβ1/FAK/PI3K/ERKs survival signaling pathways." (PMID 34685701, 2021). "In addition, IL-33 induced the tumoricidal effect of eosinophils, directly killing tumor cells by increasing the effector molecules, such as markers of degranulation (CD63, CD107a), activation (CD69), and adhesion molecules, such as CD11b/CD18 and ICAM-1." (PMID 34209038, 2021). "Tumour-derived microparticles and exosomes are also a source of various substances, including CD63, platelet-derived growth factor (PDGF), vascular endothelial growth factor (VEGF), and thrombin, that promote tumour-cell induced platelet aggregation (TCIPA) and maintain a hypercoagulable state." (PMID 33923802, 2021). "Results demonstrated that miR-1246 strongly colocalized with CD63 in tumor samples." (PMID 34572835, 2021). "Both normal and tumour‐associated EVs were strongly positive for CD9, CD81 and CD63." (PMID 34596356, 2021). "Further ImageStream analysis revealed the expression of epithelial cell adhesion molecule (EpCAM) and exosome specific surface markers, including CD9, CD63, tumor susceptibility gene 101 (TSG-101), and CD81 confirming the tumor cell-derived vesicles as exosomes." (PMID 32456301, 2020). "Examination of cluster-specific marker genes showed that tumor ECs expressed a unique set of genes such as Col18a1 and Aplnr, but also shared a number of expressed genes with venous ECs, especially with PV, such as Cd63, Ehd4, and Cd200." (PMID 32440964, 2020). "However, several studies show that Cd63 plays a crucial role in tumor cell plasticity and metastasis." (PMID 33221747, 2020). "The expression TM4SF5 could cause internalization of CD63, which resulted in the decrease of CD63 level at the membrane surface and disrupted its tumor-suppressing action." (PMID 33015133, 2020). "Immunohistochemically, the tumor cells are typically positive for NKI/C3 (CD63), CD10, and PGP9.5." (PMID 32316685, 2020). "These events led to eosinophil degranulation, as demonstrated by TEM analysis, showing emptying granules in IL-33 EO adjoining tumor cells, and by up-regulation of surface CD63, an intracellular granule marker that translocates to the cell membrane as a result of degranulation." (PMID 31717819, 2019). "Exosomes are CD63+ endosomal-derived vesicles which transfer proteins, mRNAs, and microRNAs to neighboring or distant cells to modulate immune function, angiogenesis, cell proliferation, and tumor cell invasion." (PMID 31203443, 2019). "In all tumors, tumor cells showed a distinct punctate cytoplasmic CD63 expression." (PMID 29523123, 2018). "Interestingly, we observed an increased density of CD63+ cells around blood vessels – similar to what has been reported for CD133+ tumor cells being localized in so-called perivascular niches." (PMID 29523123, 2018). "Indeed, a bispecific antibody was engineered to target CD63 on one arm thereby enabling efficient internalization of an anti-HER2 arm that targets the tumor." (PMID 29946318, 2018). "This may suggest that CD63 is important for tumor cell biology as well as for angiogenesis and neuronal survival." (PMID 29523123, 2018). "In specific, TIMP1 signaling via CD63 leads to activation of hepatic stellate cells, which create a pre-metastatic niche in the liver allowing efficient metastasis to this organ, and also induces a tumor-promoting stress response in tumor cells." (PMID 29394913, 2018). "However, to fully elucidate the prognostic value of CD63+ immune cells and CD63+ tumor cells, additional prognostic studies should be performed e.g. by confocal double-immunofluorescence analysis." (PMID 29523123, 2018). "CD63 was also expressed in tumor blood vessels as well as in neurons in the tumor periphery." (PMID 29523123, 2018).
tumor (continued). "In summary, these data indicate that CD63 is differentially over-expressed with molecules related to tumor aggressiveness and resistance and may thus contribute to a pro-tumorigenic microenvironment." (PMID 29523123, 2018). "CD63+ blood vessels were often located in relation to CD63+ tumor cells." (PMID 29523123, 2018). "In general, a weak CD63 expression was detected in a few putative invading tumor cells." (PMID 29523123, 2018). "FACS analysis confirmed that the PS-free patient (patient #19) had no residual double positive (PS + CD63) exosomes in her plasma while the patient with the relatively high residual PS (patient # 17) also expressed significant amounts of CD63-positive (tumor) exosomes." (PMID 28122335, 2017). "Furthermore, SSX2 was specifically enriched in the CD45−/EpCAM+/CD63+ subpopulation, which marks prostate-specific circulating tumor cells while differentiating from erythroid progenitor CD45−/EpCAM+ cells." (PMID 27276714, 2016). "Further studies are needed to elucidate whether the glycosylation status of CD63 plays a role in tumor cell invasion and metastatic phenotypes regulated by RPN2 in NSCLC." (PMID 25595901, 2015). "However, CD63 was excluded from the membrane surface, where it plays a tumor-suppressive role, by the expression of TM4SF5 and/or CD151." (PMID 25033048, 2014). "This action may decrease the tumor-suppressive functions by CD63, during TM4SF5-mediated liver malignancies." (PMID 25033048, 2014). "Although TM4SF5, CD151, and CD63 can localize to the membrane surface and within the endosome system, their localizations could play critical roles in tumor progression and fibrotic phenotype development in the livers." (PMID 25033048, 2014). "The CD31-positive cells (green) was co-localized with CD63 (red) signals in the tumor." (PMID 23439645, 2013). "Of the 20 known members, five – MRP1/CD9, ME491/CD63, KAI1/CD82, CD151, CD81 – may be implicated in cell migration, proliferation and tumour cell metastasis." (PMID 14735195, 2004). "Importantly, TIMP1 was shown to modulate the tumor immune microenvironment by inducing M2 macrophage polarization via CD63/β1-integrin-mediated activation of the AKT/mTOR signaling pathway, thereby promoting hepatic pre-metastatic niche (PMN) formation and metastatic colonization." (PMID 41511313, 2025). "Next, we functionally addressed the question, whether a shift to fully glycosylated TIMP-1glyc1/1 can be linked to noncanonic CD63-mediated tumor-promoting effects of TIMP-1, namely tumor cell proliferation and survival." (PMID 40345589, 2025). "In addition, we found that FAP+ CAF bound to CD63 in tumor cells by secreting the TIMP1 ligand." (PMID 37333982, 2023). "Besides, IL-33 induced a direct tumor-killing effect by enhancing the expression of effector molecules, including degranulation markers (CD63 and CD107a), activators (CD69), adhesion molecules (CD11b/CD18 and ICAM-1), cytokines (TNF-α), and effector molecules (granzyme A)." (PMID 36291105, 2022). "Therefore, these in‐silico findings suggested that the tumour‐suppressive effects of CD63 might be mediated by inflammation‐related oncogenic signalling pathways." (PMID 33277798, 2021). "Therefore, the higher levels of CD63, despite treatment, may suggest a failure to inhibit CD63-mediated signalling (which involves intracellular trafficking), thus mediating tumour survival and metastasis." (PMID 33923802, 2021). "Results of our experiments showed that CD63 expression was frequently reduced in HCC tissues compared with adjacent normal tissues, and decreased CD63 expression was significantly associated with larger tumour size, distant site metastasis and higher tumour stages of HCC." (PMID 33277798, 2021). "Additionally, atypical Gaucher cells have been described, which express some markers of tumor-associated macrophages such as CD63, CD168 and VEGF, and could participate in tumor development, as already described in hepatocellular carcinoma." (PMID 32085512, 2020).
tumor (continued). "Also in some perivascular areas, tumor cells showed an intense CD63 expression." (PMID 29523123, 2018). "Moreover, CD63+ blood vessels were also observed in the tumor periphery." (PMID 29523123, 2018). "Our data showing the existence and secretion of EVs, including CD63-positive exosomes, by metastatic OS cells opens the possibility that in OS, as in other cancers, exosomes may contribute to tumour progression and metastasis through local and distant intercellular communication." (PMID 26317203, 2015). "Post-tumor resection, serum levels of CD63+, CD41+, and CD61+ exosomes decreased, suggesting a correlation between exosome count in serum and tumor burden." (PMID 40490663, 2025). "CD9+/CD63+/CD81+ EVs (Transport‐EVs) transmit resistance, whereas CD147+/LAMB1+ EVs (Excretion‐EVs) excrete tumour‐suppressive cargos, highlighting the functional divergence of EV subtypes in GCB resistance." (PMID 41159684, 2025). "CD63 and CD9 tetraspanins promote tumor development and determine invasiveness in certain cancer types, while glycosylation, as a post-translational process, has a key role in modulating the expression and molecular function of these membrane proteins." (PMID 39766023, 2024). "CC cells were treated with HEK293-derived exosomes (size range of 118–129 nm, marker proteins CD63, TSG101) containing miR-22 which enhance the radiosensitivity of tumor cells." (PMID 39165926, 2024). "The violin diagram shows that in HNSCC tissue, macrophages highly expressed four classic marker genes (CD63, CD9, CD81, TSG101) of exosomes, suggesting that TAM-EVs are highly secreted in the tumor microenvironment." (PMID 38602536, 2024). "In contrast, EVs (size range of 70–120 nm, marker proteins CD9,CD63,TSG101) secreted by glioma-derived M2 macrophages inhibit the growth and invasion of tumor cells through the PI3K/AKT/mTOR signaling pathway." (PMID 39165926, 2024). "Western blot analysis showed that tumor cell-derived MVs expressed characteristic marker proteins TSG101 and CD63, along with high levels of EphA2." (PMID 38433190, 2024). "FMC-1807-PDX-bearing mice were intraperitoneally injected with CD63-GFP-expressing EV and sacrificed at 12- or 24-h post-injection to detect the cellular uptake of EV in multiple tissues, including the primary tumor, lung, liver, spleen and kidney." (PMID 37941082, 2023). "In a recent preclinical trial, a bispecific ADC targeting both HER2 and CD63 has showed better internalization and lysosomal accumulation in HER2-positive tumor cells." (PMID 37568702, 2023). "Among all genes connected with CD63, SAT2 is the one with the most significantly differential correlations in tumor and normal tissues." (PMID 36542714, 2022). "We observed that CA1a tumours had more localisation of CD63 and ITGAV than MB‐231 tumours, supporting our finding that increased ITGAV was exported into the cancer‐derived EVs in metastatic tumours in vivo." (PMID 35923105, 2022). "We also quantified expression of CD63, CD35/CD21, and CD69 on eosinophils during EO771 tumor growth in the lungs since these are established markers of eosinophil activation and/or secretion." (PMID 35756626, 2022). "Concomitantly, high immunopositivity to CD63 in MCs was detected along the periphery of the granules, confirming that mature granules could be a source of specific proteases during the formation of exosomes for extracellular regulation of tumor microenvironment targets." (PMID 36012196, 2022). "The results of Western blot analysis also showed that exosomes secreted from 4T1 tumor cells express CD81, CD9, CD63, and TSG101 markers along which β-actin was used as the internal control." (PMID 34194604, 2021).
tumor (continued). "To determine the in vivo relevance of the secretion of CD81+CD63+EVs, we injected two 67NR-S and one 67NR-NS cell line into the mammary fat pad of BALB/c mice and monitored the tumor growth for six weeks." (PMID 34503207, 2021). "A similar expression pattern was observed between CD63 and BIRC3 (scLink’s correlation = 0.58, adjustedP = 0 in the tumor sample)." (PMID 34252628, 2021). "Loss of sphingomyelinase, an enzyme which breaks down sphingolipid to ceramide, impairs exosome secretion of Aβ- peptides in neurons and exosomes containing CD63, CD81, Tsg101 and miRNAs in multiple tumor models." (PMID 33892745, 2021). "At the tissue level, CD9 was found to be predominantly localized at the cell membrane, whereas CD63, CD81, and CD82 were primarily found in the cytoplasm of the tumor samples." (PMID 34065085, 2021). "To mechanistically investigate the role of TSPANs in VSCC, we selected the tetraspanins CD63 and CD82 to study, as they are well characterized as having opposite roles in tumor development and prognosis in the literature." (PMID 34065085, 2021). "MM BM-mesenchymal stromal cell (MSC)-derived exosomes, defined as CD63+/CD81+, promote MM tumor growth via downregulation of a tumor suppressor miR-15a; in contrast, normal BM-MSC exosomes inhibit growth of MM cells." (PMID 33435632, 2021). "Both of the two tumor cell-derived exosomes showed positive expression of exosome markers, including HSP70, CD63, and CD9." (PMID 33644057, 2021). "Only minor differences in overall levels of tetraspanins were observed when comparing normal with disease EVs, whereby CD9 and CD63 appeared to increase, and CD81 decreased, in tumour‐stroma EVs." (PMID 34596356, 2021). "Some tetraspanins, such as TSPAN15, can enhance tumor cell proliferation ability, while other family members, such as CD9, CD63, TSPAN1, TSPAN7, and TSPAN31, can antagonize apoptosis and facilitate tumor cell survival." (PMID 34540692, 2021). "As in the blood, CD63 + exosomes were also found in saliva that have shown prognostic value in patients with OSCC whenthey are counted in serum prior to and after tumour resection surgery." (PMID 31496355, 2019). "First, after the surgical treatment the plasmatic CD63+ EXO levels dropped to lower values, suggesting that the tumour mass was at least in part responsible of the number of circulating exosomes we found before surgery." (PMID 30917536, 2019). "Cellular co-expression of TIMP-1 and CD63 as well as TIMP-1 and the tumor stem cell-related markers CD133 and Sox2 was investigated with immunofluorescence." (PMID 29523123, 2018). "This bispecific construct allows targeting a drug-conjugated tumor binding-antigen, HER2, to the lysosomal pathway by CD63." (PMID 29946318, 2018). "We describe the conditions for detection of MICA in exosomes and prove, for the first time using both techniques, the co-existence in one vesicle of exosomal markers (the tetraspanins CD9, CD63 and CD81) and an endogenously expressed tumour-derived antigen." (PMID 29720199, 2018). "For example, MES GBMs (red arrows) were enriched for CAV1, CD44, CD63, RAB27A, SDCBP and SMPDL3A, while PN (blue arrows) tumours contained higher levels of transcripts for ANXA6, CD81, hnRNPA2B1, YBX1 (RNA binding proteins) and RAB35." (PMID 30034643, 2018). "All cultures were characterized for tumor surface or stem-like marker expression, namely CD46, CD47, CD55, CD56, CD63, CD90, and CD99." (PMID 28545562, 2017). "Human tumor cell (K562, A549, and HCT116)-released exosomes showed vigorous expression of tetraspanins (CD9, CD63, and CD81) with the exception of CD9 on K562 exosomes at approx. 150 nm diameter." (PMID 27101102, 2016). "The progress of the malignant potential of GIST, connected with improving CD63 expression, is very thought-provoking, especially in light of the observations of a decline in the CD9 expression when tumours are getting more aggressive." (PMID 27795705, 2016).